LEP (leptin)
Diseases named in the same sentence as LEP in open-access papers (continued):
Sharing a sentence is not in itself a finding about the gene and the disease.
prostate carcinoma (continued). "In the subgroup analysis by tumor type, an observed association between LEP 2548A (or 19G) and risk of prostate cancer suggests that this SNP may be disease specific, because all the prostate cancer patients were Caucasian decent." (PMID 24146750, 2013). "In the present study, we tested the hypothesis, whether the proliferative effect of leptin in prostate cancer cells is linked to the stage of androgen-sensitivity in these cells." (PMID 22690216, 2012). "Therefore, the simultaneous presence of high insulin and leptin levels and low testosterone levels explains the reduced risk of incident tumours, but the increased risk of progression in existing prostate cancer tumours." (PMID 21266978, 2011). "Effects of long-term, even mild, overweight on prostate cancer risk could be mediated by several biological mechanisms, implicating sex hormones (androgens and oestrogen), leptin, and insulin-like growth factor (IGF)-I." (PMID 15150581, 2004). "Thus, low preoperative serum adiponectin and high leptin levels were significantly associated with biochemical recurrence in adipose tissue-invasive prostate cancer, suggesting that they may be useful predictors of biochemical recurrence." (PMID 39201655, 2024). "Mechanistically, we showed that Leptin, a pleiotropic adipocytokine involved in energy metabolism and oncogenesis, was highly induced by p73γ,necessary for p73γ-mediated oncogenic activity, and associated with p73α to γ isoform switch in human prostate cancer and dog lymphoma." (PMID 37650871, 2023). "We hypothesise that leptin is positively associated with risk of overall and aggressive prostate cancer and adiponectin is inversely associated with risk of overall and aggressive prostate cancer." (PMID 33431998, 2021). "There were numerous reports investigating the association of leptin or leptin receptors mRNA expression with the risk of various cancers either by immunohistochemical techniques or by RT‐PCR (as this study); however, fewer studies have been conducted on prostate cancer." (PMID 32573960, 2020). "The inverted adiponectin-to-leptin ratio is increasingly recognized as a critical biomarker that reflects a systemic metabolic state conducive to prostate cancer progression." (PMID 41555998, 2025). "Cellular invasion and migration of androgen-resistant prostate cancer cells (PC-3 and DU-145 cell lines) are attenuated by leptin in a concentration-dependent manner in prostate cancer cell lines." (PMID 39941741, 2025). "Beyond leptin and adiponectin, emerging evidence implicates additional adipokines in prostate cancer pathogenesis." (PMID 41555998, 2025). "Next, the correlation between androgen receptor expression and the combination of adiponectin and leptin levels was examined by immunostaining of prostate cancer tissue." (PMID 39201655, 2024). "In fact, prostate cancer patients suffering from MetS also report high serum leptin concentrations and low adiponectin levels, which together are associated with prostate cancer induction and growth." (PMID 38785834, 2024). "Adipokines released from adipose tissue, such as leptin and adiponectin, play an active role in the proliferation of prostate cancer cells." (PMID 39596205, 2024). "Secondly, the adipokine leptin promotes cell motility of prostate cancer cells through the PI3K/Akt/NF-κB pathway." (PMID 38993553, 2024). "In prostate cancer, adiponectin also inhibits cancer cell growth and leptin inhibits cancer cell growth as well." (PMID 39201655, 2024). "Leptin is an upstream activator of JNK and causes proliferation in an androgen-independent prostate cancer cell." (PMID 39596205, 2024). "We found that Leptin expression was low in normal human prostates but highly elevated in prostate carcinomas, which correlates well with the expression of p73γ (Leptin and p73γ panels, compare lanes 1–5 with 6–13)." (PMID 37650871, 2023).
prostate carcinoma (continued). "(F, G) The levels of p73γ, Leptin, and actin transcripts were examined in 5 normal prostates and 16 human prostate carcinomas." (PMID 37650871, 2023). "Leptin has prostate cancer-promoting effects and is positively correlated with fat mass, while adiponectin has anticancer effects and is negatively correlated with BMI." (PMID 36755926, 2023). "Another study also found that there was an inverse correlation between leptin plasma levels and weight of prostate cancer, and high plasma leptin levels suppressed cellular proliferation and angiogenesis in vivo." (PMID 36172174, 2022). "A similar positive correlation was also discovered between leptin/leptin receptor overexpression and distant metastasis in a cohort of 176 prostate cancer patients." (PMID 33799880, 2021). "Higher RNA levels of both leptin and leptin receptors were found in prostate cancer patients than in healthy controls in a study including 176 men." (PMID 33799880, 2021). "The main leptin meta-analyses included 4343 incident prostate cancer cases and 1486 aggressive prostate cancer cases." (PMID 33431998, 2021). "Leptin is elevated in obese men, and there are reports connecting leptin with increased prostate cancer cell proliferation and inhibition of apoptosis." (PMID 33921222, 2021). "In DU145 and PC-3 cell lines, leptin was shown to induce proliferation and migration of the prostate cancer cells through the PI3K and MAPK pathways." (PMID 33920379, 2021). "In prostate cancer, its effects have been demonstrated in cell culture models, where leptin stimulation increases cell growth in androgen-independent PC-3 and DU145, but not in hormone-responsive LNCaP cells." (PMID 34074045, 2021). "Serum leptin levels have been reported to be higher in prostate cancer patients than in healthy patients." (PMID 33334030, 2020). "In vitro studies suggested the role of leptin and its receptors in the development of prostate cancer." (PMID 32573960, 2020). "Prostate cancer patients undergoing ADT have leptin levels double that of those who have just undergone prostatectomy and/or radiotherapy without ADT." (PMID 32056047, 2020). "Circulating serum levels of leptin were found to be significantly higher in advanced and high‐grade prostate cancer patients." (PMID 32573960, 2020). "In the literature, there are also several reports about the role of LEP in the progression of prostate cancer." (PMID 31671654, 2019). "On the other hand, leptin treatment inhibited the anti-proliferation effect and pro-apoptosis effect (Bcl-2) of adiponectin in prostate cancer cell line." (PMID 30013512, 2018). "Although the involvement of leptin and resistin in malignancies such as breast and prostate cancers has been extensively studied, very little is known about their role in melanoma growth and chemotherapeutic outcome." (PMID 29568521, 2018). "Components of MetS are linked to an increased risk of prostate cancer and MetS-related biomarkers such as insulin, insulin-like growth factor-1 (IGF-1), leptin and adiponectin are implicated in the involvement of tumorigenesis." (PMID 27349496, 2016). "For instance, leptin and interleukin-6 showed in vitro to have a supporting activity in prostate cancer cell lines inducing proliferation, inhibiting apoptosis and increasing migration." (PMID 26846521, 2016). "Leptin was shown to induce cellular migration of human prostate cancer mediated via upregulation of αvβ3 integrin and intracellular signal transduction." (PMID 26376613, 2015). "In vivo, low-leptin ob/ob mice injected with murine androgen-insensitive prostate cancer cell line RM-1, developed larger tumours and had stronger Ki-67 staining than high-leptin db/db mice." (PMID 26376613, 2015). "In human prostate cancer and chondrosarcoma cells, leptin increased expression of αvβ3 via IRS-1/PI3K/Akt, and NFκB signaling cascades promoting cell migration." (PMID 24202338, 2013).
prostate carcinoma (continued). "In fact, the mitogenic and anti-apoptoptic effects of several adipokines, alone and combined, in prostate cancer cell growth (e.g. leptin, IL-6, insulin-like growth factor 1, IGF-1), seems to be limited to hormone-refractory prostate cancer cells." (PMID 22469146, 2012). "In conclusion, the present study showed that the effect of leptin on growth of prostate cancer cells is different according to the androgen sensitivity of the evaluated cells." (PMID 22690216, 2012). "For this purpose, we sought to evaluated any difference in response to leptin in androgen-sensitive and insensitive prostate cancer cell lines." (PMID 22690216, 2012). "We previously have shown that leptin in vitro is able to induce mitogenic actions in a group of human prostate cancer cell lines." (PMID 22690216, 2012). "Again, for prostate cancer cells, most studies reported mitogenic and antiapoptotic effect of leptin on androgen-resistant cell lines DU145 and PC-3 cells, while androgen-sensitive cell line LNCaP cells were mostly unresponsive or not tested." (PMID 22690216, 2012). "It has also been suggested that there is a strong link between leptin and cancer growth and development, with increasing evidence on the involvement of leptin on breast, ovarian, endometrial, colon, and prostate cancer." (PMID 20723213, 2010). "A multitude of other studies have demonstrated that leptin mediates a significant increase of proliferation in breast, colon, esophagal and prostate cancer cells, too." (PMID 20030801, 2009). "In contrast, leptin caused a significant dose-dependent decrease in migration and invasion solely of PC-3 and DU145 prostate carcinoma cell lines." (PMID 20030801, 2009). "Clinical studies focused on comparison of serum leptin levels in benign prostatic hyperplasia, prostate cancer and control healthy subjects." (PMID 21566743, 2008). "Additionally, the proliferation of androgen-dependent and independent prostate cancer cell lines was observed in the presence of nanogram concentrations of leptin." (PMID 39941741, 2025). "Our findings support the hypothesis that a subset of patients with advanced prostate cancer and CHD share a biologic vulnerability linked by adiposity and leptin." (PMID 39557398, 2025). "Serum levels of leptin positively correlate with prostate cancer development." (PMID 39941741, 2025). "Here we explore whether leptin, as a marker and mediator of adiposity, could link prostate cancer to CHD." (PMID 39557398, 2025). "Thus, the combination of serum adiponectin and leptin levels in patients with preoperative prostate cancer is a promising predictor of biochemical recurrence." (PMID 39201655, 2024). "Previous meta-analyses have reported that increased adiponectin correlates slightly inversely with prostate cancer prognosis and increased leptin correlates slightly with high-grade prostate cancer; however, most comparisons have been made with Gleason scores or healthy men." (PMID 39201655, 2024). "A previous report also examined the correlation of adiponectin and leptin concentrations with prostate cancer progression to CRPC and overall survival (OS) but reported that each alone did not contribute to the correlation, supporting the results of a previous report." (PMID 39201655, 2024). "Moreover, we found that p73α to γ isoform switch was detected in a subset of dog lymphomas and human prostate carcinomas along with elevated expression of Leptin." (PMID 37650871, 2023). "Leptin content is higher in patients with prostate cancer than in those with benign prostate hyperplasia, indicating that leptin functions as a biomarker for prostate cancer staging." (PMID 36980222, 2023). "When comparing prostate cancer patients (including advanced stages) to patients with benign prostate hyperplasia or early stage prostate cancer, leptin expression was increased, indicating leptin expression can be used as a biomarker for prostate cancer staging and prognosis." (PMID 35164764, 2022).
prostate carcinoma (continued). "The negative association between BMI and prostate cancer risk was attenuated after adjustment for BioT or leptin." (PMID 36558416, 2022). "For leptin and overall prostate cancer, the overall fixed effect OR was consistent with the null hypothesis (OR 1.00, 95% CI 0.98 to 1.02 per 2.5 ng/ml increase in leptin, p = 0.84)." (PMID 33431998, 2021). "For instance, leptin stimulates prostate cancer cell proliferation and migration through STAT3." (PMID 34025420, 2021). "The effect of leptin on prostate cancer progression was assessed in DU-145 and PC3 cell lines." (PMID 33799880, 2021). "Protein restriction improves insulin and leptin sensitivity in patients with prostate cancer." (PMID 34766923, 2021). "In vitro studies have documented the mitogenic role of leptin in prostate cancer cell lines." (PMID 32573960, 2020). "In 2011, an excess of adipose tissue and high serum leptin levels were directly corelated to prostate cancer aggressiveness, rather than being seen as risk factors." (PMID 33334030, 2020). "Studies of leptin levels and prostate cancer aggressiveness have produced mixed results." (PMID 32056047, 2020). "Likewise, in other reports, serum leptin levels were observed to be significantly higher in advanced prostate cancer relative to confined tumors." (PMID 32573960, 2020). "Moreover, flow cytometry with a specific antibody for Cleaved PARP-1, an apoptosis marker, confirmed the activation of apoptosis in leptin-exposed LNCaP line of prostate cancer cells." (PMID 31671654, 2019). "The main aims of the study were to assess the circulating level of leptin and omentin as well as related proteins: HGF and VEGF in men with prostate cancer and benign prostate hyperplasia, and to study the associations between their concentrations and PSA level." (PMID 30186533, 2018). "In prostate cancer cell lines, leptin treatment increased TGFB1 secretion 2-3-fold in a time and dose dependent manner, and in A549 lung cancer cells, leptin exposure increased TGFB1 expression, enhanced metastasis and EMT induction that was inhibited by siRNA against TGFB1." (PMID 28542577, 2017). "Prostate cancer patients affected by MS has high levels of leptin and low levels of adiponectin." (PMID 28389628, 2017). "Previous studies have shown that leptin can induce cancer cell migration via the MAP kinase in prostate cancer, via the AKT pathway in endothelial cells, via the NF-kB pathway in glioma cells, and via the JAK/STAT, PI3K/AKT, and MAPK pathways in hepatocellular carcinoma cells." (PMID 29212170, 2017). "Interestingly, our meta-analysis results were consistent with previous studies reporting that patients with hepatocellular carcinoma or prostate cancer have higher leptin levels than the normal population does." (PMID 28160559, 2017). "Lan-1 has been shown to inhibit leptin signalling in the prostate cancer cell line LNCaP." (PMID 27480179, 2016). "Furthermore, men with high-volume prostate cancer (greater than 0.5cc in volume or extraprostatic disease) had higher serum leptin concentrations than their low volume counterparts when stratified by age, testosterone level, height and BMI." (PMID 26376613, 2015). "Given the complexity of metabolic cancer pathways, it is possible that leptin may have varying effects on prostate cancer at different stages of its development, a point that may be addressed by further epidemiological studies." (PMID 26376613, 2015). "However, epidemiological evidence supports leptin influence on the promotion of prostate cancer and developing larger tumours." (PMID 26376613, 2015). "In a view of recent findings linking leptin signalling to the sphingolipid pathway it may be reasonable to investigate this link in prostate cancer, specifically in a view of developing new chemo- or radio-sensitizing therapies." (PMID 26376613, 2015).
prostate carcinoma (continued). "We applied all four GSA methods to analyze a real Affymetrix microarray dataset consisting of genome-wide transcriptomic measurements of prostate tumor samples from African-American prostate cancer patients against the continuous phenotype of the human leptin gene (LEP) expression values." (PMID 23815123, 2013). "In conclusion, this meta-analysis found that the LEP 2548AA genotype was associated with a weakly increased risk of cancer, mainly for prostate cancer, while LEPR Q223R was not." (PMID 24146750, 2013). "Three human prostate cancer cell lines were treated with increasing doses of recombinant leptin." (PMID 22690216, 2012). "The leptin SNP at position -2548 was proposed as a susceptibility locus for prostate cancer, albeit our data do not support this contention." (PMID 22792137, 2012). "Our findings show that SNPs in genes from adipokine pathways (leptin, interleukin-6, fibroblast growth factor 2, osteopontin, and insulin growth factor) may influence the development of prostate cancer and aggressive disease." (PMID 22792137, 2012). "The negative impact of leptin on PC might involve an anti-proliferative and anti-angiogenetic effect of leptin on prostate cancer cells, but the underlying mechanisms remain unclear." (PMID 38831447, 2024). "Furthermore, to determine whether the p73γ-Leptin axis plays a role in cancer progression, we examined whether the expression pattern of Leptin is correlated with that of p73γ in human prostate carcinomas and dog lymphomas." (PMID 37650871, 2023). "However, a recent meta-analysis of prospective epidemiological studies found a weak, negative association between plasma leptin and prostate cancer risk." (PMID 36558416, 2022). "Finally, adiponectin levels are inversely and leptin levels directly correlated with prostate cancer grade in some cohorts suggesting that effects of SH‐BC‐893 on these adipokines may contribute to its ability to suppress prostate cancer growth." (PMID 34231322, 2021). "However, there was some evidence of asymmetry in studies of aggressive prostate cancer; for leptin this asymmetry was to the right, or towards positive associations in smaller studies, and for adiponectin this was to the left, or towards inverse associations in smaller studies." (PMID 33431998, 2021). "Moreover, elevated levels of plasma leptin was detected in prostate cancer patients, which might have a positive correlation with PCa development." (PMID 33046976, 2020). "In the meta-analysis, LEP rs7799039 (allele contrast: OR 1.133, 95%CI 1.024-1.254), ADIPOQ rs2241766 (allele contrast: OR 1.201, 95%CI 1.015-1.422) and ADIPOR1 rs10920531 (allele contrast: OR 1.184, 95%CI 1.075-1.305) variants were identified to be correlated with increased risk of prostate cancer." (PMID 27768592, 2016). "A meta-analysis that included 5 articles related to this SNP and colorectal carcinoma risk and 3 studies related to prostate cancer susceptibility concluded that this alteration in LEP may increase the risk for prostate cancer but not for colorectal carcinoma." (PMID 25810718, 2015). "Therefore, the main goal of our study was to assess the effects of preadipocyte and adipocyte secreted factors in the proliferation, migration and invasiveness of prostate cancer cells, and the effects of the adiposity signals, insulin and leptin, in cell proliferation." (PMID 25928422, 2015). "Similarly, the tumorigenic role of LEP -2548G/A was also found in prostate cancer in American." (PMID 23593308, 2013). "The present study was undertaken to further investigate the effect of leptin on growth of prostate cancer cells as we have tested the hypothesis whether the increase in prostate cancer growth by leptin might be different in androgen-resistant cells compared to androgen-sensitive cells." (PMID 22690216, 2012). "In addition, new evidence suggests that leptin could be involved in tumorigenesis, especially in the development of breast, colorectal and prostate cancers." (PMID 19223908, 2009).